GABRB2 (gamma-aminobutyric acid type A receptor subunit beta2)
Diseases named in the same sentence as GABRB2 in open-access papers (continued):
Sharing a sentence is not in itself a finding about the gene and the disease.
epilepsy (17 papers, 2016 to 2025). A brain disorder characterized by episodes of abnormally increased neuronal discharge resulting in transient episodes of sensory or motor neurological dysfunction, or psychic dysfunction. "Our findings shed light on the impact of gain-of-function GABRB2 variants, which can lead to catastrophic early onset epilepsies, severe intellectual disability, movement disorders and high risk of early death." (PMID 38996765, 2024). "Traditionally, it was believed that GABRB2 variants primarily led to loss of receptor function, resulting in hyperexcitation in neuronal networks and subsequent epilepsy." (PMID 38996765, 2024). "We collected a cohort of 42 individuals (18 females and 24 males) with neurodevelopmental disorders and epilepsy attributed to variants in the GABRB2 gene." (PMID 38996765, 2024). "In our previous study of other types of GABAA receptor-related epilepsy, we found that patients with GABRB2 and GABRB3 variant-related epilepsy patients also had a good response to valproate and levetiracetam." (PMID 35359574, 2022). "Mutations in GABRB2 genes have been reported to be associated with intellectual disability and epilepsy." (PMID 29747637, 2018). "The de novo mutation β1(F246S) was identified in a case of infantile spasms, whereas a de novo mutation in exon 4 of GABRB2 (β2(M79T)) was discovered in a patient with intellectual disability and epilepsy." (PMID 27622563, 2016). "Like the (+)β3Y302C mutation, the GABRB2(M79T) mutation associated with intellectual disability and epilepsy which lies in the β2-sheet at the β+/α- interface, is expected to cause rearrangements within the Cys-loop and M2-M3 loop." (PMID 27622563, 2016). "We found that variants in the epilepsy-associated genes GABRA1, GABRB3 and GABRG2 were mainly present in the ESP variants, but the GEC cohort contained epilepsy-associated GABRA6, GABRB1, and GABRB2 and non-epilepsy- associated GABRA4, GABRA5, and GABRG3 genes." (PMID 27622563, 2016). "Similarly, Y277C mutation in GABRB2 or GABRB3 lead to epilepsy (74, –76)." (PMID 41129221, 2025). "Also Gabrb2 (Gamma-aminobutyric acid receptor subunit beta-2) and Scn9a (Sodium channel protein type 9 subunit alpha) genes, which are implicated in epilepsy, showed altered expression in the transgenic animals (2−∆∆Ct = 0.87, p = 0.23; 2−∆∆Ct = 1.26, p = 0.136, respectively)." (PMID 31698854, 2019). "Variants in the GABRB2 gene, which encodes the GABAA receptor β2 subunit, have been implicated in a broad range of neurodevelopmental disorders, epilepsies, and movement disorders." (PMID 38996765, 2024). "It is well known that mutations/variants in GABRA1, GABRB2, GABRB3, or GABRG2 produce several different types of epilepsy." (PMID 34095830, 2021). "The currently known epilepsy-associated variants identified in GABAA receptor subunits are predominantly distributed in the four genes (GABRA1, GABRB2, GABRB3 and GABRG2) that code for the most commonly distributed receptor isoforms." (PMID 34095830, 2021). "With regards to GABRB2, epilepsy is present in almost all the patients so far described, but the age of onset in patient 8 is later (2 years) than that (within the first year of life) reported." (PMID 31344879, 2019). "After searching in DrugBank, we retrieved a total of 47 anti-epileptic drugs and 151 targets, of which identified 17 target genes (CACNA1A, CHRNA4,CHRNA7,GABRA1,GABRA2,GABRB2,GABRG2,GRIK1,GRIN1,GRIN2B,KCNQ2,KCNQ3,SCN1A,SCN2A, SCN3A,SCN8A and SCN9A) were overlapped with risk genes of epilepsy." (PMID 36006933, 2022). "Additionally, four of the brain-expressed, constrained genes that we identified through the new paralog conservation test and presented in the first pre-print version of the manuscript, CHD3, CACNA1E, PHIP, and GABRB2, were recently shown to be significantly enriched in NDDs with epilepsy." (PMID 32183904, 2020).
epilepsy (continued). "The observation of audiogenic epilepsy in only KO but not HT mice suggests that a deeper GABAergic deficit than that inflicted by Gabrb2 hemizygosity would be required for epileptogenesis." (PMID 30013074, 2018).
Anxiety (6 papers, 2016 to 2022). Intense feelings of nervousness, tension, or panic often arise in response to interpersonal stresses. "ERBB4 is a major gene involved in fear responses, and the GABRB2 gene is reportedly associated with behavioral responses to anxiety in chickens and mice." (PMID 34072132, 2021). "The closely-related GABRB2 is also associated with anxiety in chickens." (PMID 32842956, 2020). "Here, two genes also discovered in our study LOC770352 and GABRB2, were identified as top candidate genes affecting stress and anxiety behavior." (PMID 36061196, 2022). "It is also interesting that a related subunit (GABRB2) has recently been shown to be strongly related to chicken anxiety behaviour and the GABA-signalling pathway has been found to be clearly linked to domestication effects on stress in chickens." (PMID 27853585, 2016). "As expected, Gabrb2 KO mice displayed changes in anxiety-like and depression-like emotions in contrast with PMDD symptoms; changes in the social, learning, and memory abilities similar to PMDD symptoms; changes in pain threshold opposite to PMDD symptoms, hence reducing pain sensitivity." (PMID 36287173, 2022).
depression (6 papers, 2014 to 2023). "Other neurotransmitter genes Gabrb2 and Chrm2 were also modulated across treatment groups and warrant further exploration as they are associated with depression related clinical conditions." (PMID 25165739, 2014). "Besides, the actual literature describes some of the genes (RORA, Gabrb2, Npas4, and Junb) being associated with depression-like behavior." (PMID 25400562, 2014). "Also, GABRB2 is associated with other neuropsychiatric disorders, including bipolar disorder, epilepsy, autism spectrum disorder, Alzheimer's disease, frontotemporal dementia, substance dependence, depression, and internet gaming disorder." (PMID 36287173, 2022).
mental disorder (4 papers, 2007 to 2025). A disease that has its basis in the disruption of mental process. "With the employment of recurrent CNV markers, the present study has established for the first time the genetic associations between CN-gains in GABRB2 and two different psychiatric disorders, namely SCZ and PMDD in face of the effects of active recombination and natural selection on this gene." (PMID 32695026, 2020). "Given the functional significance of GABRB2 in the central nervous system, sequence and structural alterations could lead to functional perturbations of the gene, and thereby associations with psychiatric disorders." (PMID 32695026, 2020). "Both GABRB2 and ADRA1A have been reported to be associated with several psychiatric disorders: the former with SZ, BP, FTD and ASD and the latter with attention deficit hyperactivity disorder (ADHD), SZ and generalized anxiety disorder (GAD), thus making them good candidates for the DKO phenotypes." (PMID 39875098, 2025). "GRIA1 and GABRB2 are relevant to mental disorders supported by multiple evidences." (PMID 24901472, 2014).
thyroid cancer (4 papers, 2016 to 2025). "Regarding the role of these genes in cancer, there has been only one report associating GABRB2 overexpression with lymph node metastasis in thyroid cancer." (PMID 35877232, 2022). "It was also demonstrated that GABRB2 mRNA expression positively correlates with lymph nodes, and it is relevant for the proliferation, migration, invasion and apoptosis of human thyroid cancer cell lines." (PMID 37372430, 2023). "Furthermore, prognostic ROC curves based on the GEO validation set demonstrated that CYP1B1, GABRB2, and TNFSF15 were significantly associated with thyroid cancer diagnosis (AUC exceeding 0.86)." (PMID 40900788, 2025). "A recent study revealed that GABRB2 is highly upregulated in thyroid cancer." (PMID 27793213, 2016). "CYP1B1, GABRB2, and TNFSF15 have been identified as significant target genes that can collectively predict the prognosis of thyroid cancer and possess high clinical value." (PMID 40900788, 2025). "Through computational network toxicology analysis, this study identifies CYP1B1, GABRB2, and TNFSF15 as potential molecular targets mediating DEHP’s effects in thyroid cancer." (PMID 40900788, 2025).
Alzheimer disease (3 papers, 2013 to 2022). A progressive, neurodegenerative disease characterized by loss of function and death of nerve cells in several areas of the brain leading to loss of cognitive function such as memory and language.
Dravet syndrome (3 papers, 2021 to 2022). "There are variants in GABRA1, GABRB2 or GABRG2 that are all associated with Dravet syndrome." (PMID 34095830, 2021). "Mutations in GABRs, especially in GABRA1, GABRB2, GABRB3, and GABRG2, impair GABAergic signaling and are frequently associated with DEEs such as Dravet syndrome and Lennox–Gastaut syndrome, as GABAergic signaling is critical for early brain development." (PMID 36077081, 2022). "In this study, we identified nine patients with Dravet syndrome caused by variants in three relevant, but different, genes, GABRA1, GABRB2 or GABRG2." (PMID 34095830, 2021). "Next-generation sequencing on 870 patients with Dravet syndrome identified nine variants in GABRA1, GABRB2 and GABRG2 genes, which encode the most common α1β2γ2 GABAA receptor in the CNS." (PMID 34095830, 2021). "Using the advantage of next-generation sequencing (NGS) technologies, we discovered nine novel de novo variants in GABRA1, GABRB2 and GABRG2 that were associated with Dravet syndrome and code for subunits that form the most common GABAA receptor (the α1β2γ2 receptor)." (PMID 34095830, 2021). "Recently, GABAA receptor subunit genes (GABRs) encoding α1 (GABRA1), β3 (GABRB3) and γ2 (GABRG2), but not β2 (GABRB2) or β1 (GABRB1), subunits are frequently associated with Dravet syndrome or Dravet syndrome-like phenotype." (PMID 34095830, 2021).
epilepsy syndrome (3 papers, 2021 to 2026). A syndrome that has a characteristic cluster of clinical features and/or lectroencephalographic (EEG) findings that reflect underlying epileptic activity. "Among the common GABR genes with widespread distribution in the CNS and association with inherited epilepsy syndromes are GABRA1, GABRB2 and GABRG2." (PMID 34095830, 2021). "Intriguingly, early-onset DEEs were frequently observed for both individuals with GABRB2 and GABRB3 GOF, but while the peculiar epilepsy syndrome EIMFS was more prevalent in the GABRB3 GOF sub-cohort, EIDEE with a burst suppression pattern occurred at a higher frequency in the GABRB2 GOF group." (PMID 38996765, 2024).
epileptic encephalopathies (3 papers, 2022 to 2024). "The phenotypic spectrum observed for GABRG2 variants, ranging from febrile seizures to epileptic encephalopathy, is similar to those of the other GABAA receptor genes GABRA1, GABRB2, and GABRB3." (PMID 35359574, 2022). "Encephalopathy is characteristic of 112 IMDs (19%) that are often classified as developmental and epileptic encephalopathies (DEE) (e.g., early infantile epileptic encephalopathies due to GABRA1, GABRB1, GABRB2 or GABRB3 pathogenic variants)." (PMID 35328062, 2022). "Variants in GABRB2, encoding the β2 subunit of the γ-aminobutyric acid type A (GABAA) receptor, can result in a diverse range of conditions, ranging from febrile seizures to severe developmental and epileptic encephalopathies." (PMID 38996765, 2024).
psychosis (3 papers, 2009 to 2025). "In conclusion, the present study demonstrated that GABRB2 is significantly associated with altruism and psychosis in SCZ." (PMID 23638040, 2013). "The present study considered the possibility of cognition-related GABRB2 involvement by examining the association of GABRB2 with psychosis and altruism, respectively representing psychiatric and psychological facets of social cognition." (PMID 23638040, 2013). "GABRB2 haplotype association in psychosis severity-based subgroups." (PMID 23638040, 2013). "Furthermore, the associations of GABRB2 with both psychosis and altruism suggest its fundamental association with the entire psychiatric to psychological spectrum of social cognition, thus establishing GABRB2 involvement at the level of social cognition." (PMID 23638040, 2013). "Importantly, this finding suggested that the association of GABRB2 with SCZ is centered at the core symptom of psychosis of the disorder." (PMID 23638040, 2013). "In this regard, the SNPs in GABRB2 that are strongly associated with SCZ provide uniquely advantageous genetic probes to search for common genetic elements between altruism and psychosis." (PMID 23638040, 2013). "The present study therefore has rendered even more unambiguous the importance of the SNPs in this region of GABRB2 with respect to isoform expressions and the etiologies of the two major psychotic disorders." (PMID 19763268, 2009). "This would explain the striking involvement of the same polymorphisms of GABRB2 and of COMT in both SCZ-psychosis and altruism, which may be viewed respectively as psychiatric and psychological manifestations of social cognition." (PMID 23638040, 2013). "Therefore, these first reports of association between GABRB2 and psychosis in SCZ were cross-corroborated using two different measures of psychosis in two different ethnic populations." (PMID 23638040, 2013). "Importantly, the association was found across the breadth of the psychiatric (psychosis) to psychological (altruism) spectrum of social cognition suggesting GABRB2 involvement in human cognition." (PMID 23638040, 2013). "In the present study, the possible correlation between psychosis and SNPs in the SCZ-associated GABRB2 gene was examined with respect to the severity of psychosis assessed on the basis of Positive and Negative Syndrome Scale (PANSS) and antipsychotics treatment dosages administered to SCZ patients." (PMID 23638040, 2013). "Since the GABRB2-SCZ associations were strong among schizophrenics with severe psychosis but not schizophrenics with only mild psychosis based on the PANSS scores, the findings indicated that the association of GABRB2 with SCZ is centered at the core symptom of psychosis of the disorder." (PMID 23638040, 2013). "Despite GABRB2 not being a susceptibility gene in the Lebanese population, in Han Chinese and the US populations, GABRB2 was significantly correlated with both psychosis and altruism, specifically in case of severe psychosis rather than mild psychosis." (PMID 40977746, 2025).
brain tumors (2 papers, 2023 to 2024). "Conversely, GABRB2 was downregulated in colorectal cancer, brain tumors, and kidney tumors." (PMID 37629695, 2023).
frontotemporal dementia (2 papers, 2018 to 2025). Frontotemporal dementia (FTD) comprises a group of neurodegenerative disorders, characterized by progressive changes in behavior, executive dysfunction and language impairment, as a result of degeneration of the medial prefrontal and frontoinsular cortices. "Genome wide association analyses reveal that common variants within GABRB2 are associated with increased risk for frontotemporal dementia (P < 1 × 10−3)." (PMID 30546007, 2018).
heroin addiction (2 papers, 2015 to 2020). "Taken together, these results suggested the strong link of the S1-S29 segment in GABRB2 with susceptibility to heroin dependence." (PMID 26561861, 2015). "We examined the role of in GABRB2 in susceptibility to heroin dependence in the Han Chinese population." (PMID 26561861, 2015). "In this study, we explored the role of intronic single nucleotide polymorphisms (SNPs) in GABRB2 in susceptibility to heroin dependence." (PMID 26561861, 2015). "Although role of GABRB2 in susceptibility to heroin dependence is unclear, twin studies have suggested that a common, heritable genetic factor confers a strong risk to substance dependence, while heroin dependence has been shown to possess a relatively high level of heritability (40–60%)." (PMID 26561861, 2015). "In conclusion, significant association was found with haplotypes of the S1-S29 segment in GABRB2 for heroin dependence in Han Chinese population." (PMID 26561861, 2015). "Moreover, significant association of GABRB2 with opioid (heroin and cocaine) dependence has been detected in the European and African American populations, though significant association of this gene with heroin dependence alone has not been found in the Han Chinese population." (PMID 26561861, 2015).
mood disorder (2 papers, 2014 to 2022). A cognitive disorder a disturbance in which the person's mood is hypothesized to be the main underlying feature. "Corresponding to our findings Gabrb2 was found to be decreased in the brain in mood disorders." (PMID 25400562, 2014).
thyroid tumor (2 papers, 2017 to 2025). A benign or malignant neoplasm affecting the thyroid gland. "The T3 receptors interaction with its promoter to regulate fibroblast growth factor expression in thyroid cells, and the finding that T3 receptor mutations enhance phosphatidylinositol 3-kinase signaling leading to thyroid tumors, directly intersect with our analysis of GABRB2." (PMID 40900788, 2025). "Previously, we pointed out GABRB2 and HMGA2 as potential diagnostic makers in thyroid tumors." (PMID 28469731, 2017).
alcohol-use disorder (1 paper, 2016). "Pafah1b1 has been shown to be co-expressed with GABA type-A receptor subunits (specifically Gabra1, Gabrb2, and Gabrg2), a family of neurochemical receptors associated with alcohol-use disorder." (PMID 26834590, 2016).
Alpers syndrome (1 paper, 2021). A cerebral degeneration that results in progressive degeneration of grey matter in the cerebrum and has_symptom convulsions. "In 2020, WES revealed a de novo missense variant of GABRB2 (NM_021911.2: c.784G>T, p[Val262Phe]) in a child presenting with daily MSE and RHADS, that was associated with Alpers’ syndrome phenotype." (PMID 34690748, 2021). "Variants in PARS2, CARS2, GABRB2, FARS2, and NARS2 were also reported in Alpers’ syndrome patients." (PMID 34690748, 2021). "In recent years, with the advancement of genetic testing technology, Alpers syndrome caused by NON-POLG genes has also been continuously reported, including mitochondrial aminoacyl transfer RNA synthetase related genes (PARS2, CARS2, FARS2 and NARS2) and γ-GABA receptor related genes Gene (GABRB2)." (PMID 34690748, 2021).
colon adenocarcinoma (1 paper, 2024). "For example, the expression of GABRB2 and GABRB3 is associated with colon adenocarcinoma occurrence, and a low expression of GABRB1 correlates with patient survival in that cancer type." (PMID 39595908, 2024).
medulloblastoma (1 paper, 2024). A malignant, invasive embryonal neoplasm arising from the cerebellum. "Here, we show the expression of genes encoding β subunits of the GABAA receptor, namely GABRB1, GABRB2, and GABRB3, across the four different molecular subgroups of medulloblastoma (MB), which is the most common malignant pediatric brain tumor." (PMID 39595908, 2024).
Osteochondrosis (1 paper, 2025). Abnormal growth ossification centers in children. "In the present study, among the genes nearby the associated SNP on chromosome 14, the genes GABRA1, GABRB2 and, especially, GABRA6 have previously been suggested to be associated with osteochondrosis in Standardbreds, and Hanoverian warmblood horses (GABRA6) (Naccache, Metzger, and Distl 2018)." (PMID 39754479, 2025).